PTX3 (pentraxin 3)
Diseases named in the same sentence as PTX3 in open-access papers (continued):
Sharing a sentence is not in itself a finding about the gene and the disease.
cancer (continued). "PTX3 deficiency was linked to cancer-related inflammation, angiogenesis, and mutations in models of skin cancer." (PMID 32078718, 2020). "Conversely, human PTX3 (hPTX3) upregulation causes the elongation of primary cilia in different FGF-dependent cancer cell lines, including TRAMP-C2 prostate cancer cells that originate from the transgenic adenocarcinoma of the mouse prostate (TRAMP) model." (PMID 32630309, 2020). "Conversely, PTX3 upregulation causes the elongation of primary cilium in FGF-dependent cancer cells." (PMID 32630309, 2020). "A ROC curve analysis was carried out to further validate the association of PTX3 serum levels with the cancer-specific survival." (PMID 32345771, 2020). "Evidence for the close association between the elevated expression of PTX3 and cancer-related inflammation in various malignancies suggests its clinical significance." (PMID 24457902, 2014). "In addition to its correlation with cancer aggressiveness, PTX3 expression has been linked to the differentiation status of cancer cells." (PMID 39594709, 2024). "Similarly, the TLR superfamily, which primarily functions as an immune receptor, has been linked to cancer immunity, with PTX3 influencing the activity of specific TLRs." (PMID 39594709, 2024). "Notably, the analysis of immune cell components exhibited that PTX3 was positively associated with most immune cells in most cancers, except TGCT." (PMID 36139597, 2022). "In addition, PTX3 levels were critically associated with immune cell components and immune scores, and PTX3 strongly coexpressed with immune-related genes in TCGA cancers." (PMID 36139597, 2022). "Yu and colleagues underlined that inhibition of miR-224 further targets PTX-3 gene and may prevent carcinoma progression in cervical tissue, therefore opening the road to researching potential therapeutic targets based on microRNAs and PTX-3." (PMID 36499628, 2022). "This encodes a pentraxin-3 protein that is an essential mediator of innate resistance to different pathogens of fungal, bacterial, and viral origin, and is involved in the regulation of inflammation, angiogenesis, tissue remodeling, and cancers." (PMID 34946887, 2021). "In other cancer types the high intratumoral expression of PTX3 is associated with poor prognosis." (PMID 32345771, 2020). "The increased expression of PTX3 and its close association with cancer-related inflammation informs its clinical importance and the need for therapeutic approaches targeting PTX3 or its mediators in cancer." (PMID 30740360, 2019). "In addition, inflammation-associated diseases, including cardiovascular disease and cancer, are correlated with the expression of PTX3." (PMID 28489600, 2017). "Thus, it would be an important issue to determine the association between dysregulated calcium signals, PTX3 activation and cancer prognosis." (PMID 25797258, 2015). "Likewise, the mutation of PTX3 can influence the prognosis of patients in several cancers." (PMID 36139597, 2022). "In this study, we identify a 4-protein sEV biomarker panel (thrombospondin-1, nidogen-1, pentraxin-3, and versican) based on proteomic profiles obtained from an isogenic cancer cell line model." (PMID 41881025, 2026). "Higher circulating PTX3 concentrations have been reported in patients with malignant tumors, particularly in more advanced disease stages." (PMID 41373493, 2025). "For example, in CRC, PTX3 silencing due to promoter hypermethylation promoted cancer development and progression, while another study reported higher peripheral PTX3 levels in CRC patients compared to healthy controls." (PMID 41479916, 2025). "Given the widespread use of immunotherapy in cancer treatment and the critical role PTX3 plays in the immune system, there is significant potential for PTX3 to serve as a biomarker for predicting cancer prognosis." (PMID 41479916, 2025).
cancer (continued). "The overexpressed PTX3 in cancer cell promotes stemness, EMT, migration, and invasion, which is inhibited by rBmK AGAP through NF-κB and Wnt/β-catenin signaling pathway." (PMID 41479916, 2025). "We hope this review will provide a relevant basis for developing PTX3 or its regulators as potential therapeutic targets against cancer." (PMID 41479916, 2025). "PTX3 is involved in cancer-associated inflammation, upregulated in the surgical margins of advanced OSCC, and correlates with cancer recurrence and progression." (PMID 40386053, 2025). "This review provides a comprehensive overview of the multifaceted roles of PTX3 in various cancers, while also summarizing its functions in other physiological or pathological contexts." (PMID 41479916, 2025). "Differential analysis between high-risk and low-risk cancer cells revealed that high-risk cancer cells exhibited elevated expression of genes associated with M2 macrophages, including CXCL2, IL6R, CXCL8, GDF15, CD68, and PTX3." (PMID 41034991, 2025). "PTX3 levels also fluctuate in response to drugs targeting cancer and stroma, and these changes can be easily measured in blood to monitor treatment effects." (PMID 40191200, 2025). "The promoter region and the CpG island of PTX3 are highly methylated in CRC, leading to PTX3 silencing, cancer development and growth." (PMID 41479916, 2025). "For example, HY-PDT increases pro-inflammatory cytokines like IL-8 and IL-6 in cancer cells, while reducing immunosuppressive factors such as PTX3." (PMID 39857765, 2025). "Given its involvement in tumorigenesis-related pathways, PTX3’s relationship with cancer is complex." (PMID 41479916, 2025). "PTX3 appears to serve as a crucial link between inflammation and tumorigenesis, exerting protumoral effects through cancer-related inflammation." (PMID 39594709, 2024). "In a comprehensive pan-cancer analysis, high PTX3 RNA expression was similarly associated with worse survival across various malignant tumors, leading the authors to propose PTX3 as a potential pan-cancer prognostic marker." (PMID 39594709, 2024). "While the studies included in this analysis focused on the relationship between high PTX3 protein expression and poor survival outcomes, there is also evidence linking PTX3 RNA expression with survival in cancer patients." (PMID 39594709, 2024). "HMW-HA, a major component of HC-HA/PTX3, was suggested to attenuate inflammatory pain and neuropathic pain induced by the cancer chemotherapy paclitaxel." (PMID 39671234, 2024). "In the diaphragm, trachea, intestine, and skin, organs extensively utilized for studies of lymphatic organization and function (e.g., in development, inflammation, and cancer), PTX3 was localized in the ECM surrounding lymphatic terminals and LEC sprouting." (PMID 39640269, 2024). "Depending on the cellular context, PTX3 has protective and pro-tumorigenic effects on various cancers." (PMID 38474359, 2024). "Taken together, in addition to the discovery of the direct effect of PTX3 on cancer cells and macrophages, recent evidence potentially supports an effect of CD44 and PTX3 on regulating Treg activation or differentiation." (PMID 38243273, 2024). "The authors of this opposing report demonstrated increased complement activation and a higher incidence of cancer development in PTX3 knockout mice." (PMID 39594709, 2024). "Paradoxically, PTX3 can exhibit both suppressive and promotive effects on the progression of cancer." (PMID 39187920, 2024). "Both in cell lines and tissue samples, PTX3 was more highly expressed in cancer cells than in healthy ones." (PMID 38339243, 2024). "On the other hand, PTX3 was found elevated in PDAC tissue and associated with an increased capacity of cancer cells to invade ECM." (PMID 39575252, 2024). "Through this meta-analysis, we aim to comprehensively assess the prognostic significance of PTX3 protein expression in human malignancies and evaluate its potential as a pan-cancer prognostic marker." (PMID 39594709, 2024).
cancer (continued). "As previously noted, PTX3 exhibits both protumoral and antitumoral effects, and there are only a limited number of studies on its prognostic significance in cancer." (PMID 39594709, 2024). "Its widespread applicability further underscores PTX3’s potential as a superior biomarker for cancer prognosis." (PMID 39594709, 2024). "Of note, PTX3 cross talks to components of the complement system to control cancer-related inflammation and disposal of pathogens." (PMID 37885881, 2023). "Surprisingly, PTX3 reduces the production of cell cycle-related proteins during the G2/M phase, which, in turn, prevents cancer from proliferating and metastasizing." (PMID 38136377, 2023). "This research was conducted on 184 patients with diagnosed CRC and a control group consisting of 216 healthy participants and confirmed that Pentraxin 3 occurs in higher concentrations in the blood of cancer patients." (PMID 38136377, 2023). "It is well known that PTX3 modulates the cancer-related inflammation or angiogenesis involved in the carcinogenetic process of several types of cancer." (PMID 37025408, 2023). "We also found that among four biomarkers associated with cancer cachexia, the combinations of cachexia and CRP, PTX‐3, or OPN expression levels were associated with patient prognosis." (PMID 37712645, 2023). "Long pentraxin 3, an acute phase reactant, is involved in several aspects of cancer progression, such as angiogenesis and immune modulation." (PMID 37223632, 2023). "Logistic regression analysis identified the following factors as associated with cancer cachexia: ghrelin (p = 0.041), CRP (p = 0.030), PTX‐3 (p = 0.045), and OPN (p = 0.052)." (PMID 37712645, 2023). "It has been shown that PTX3 stimulates cancer cell proliferation, apoptosis, and metastasis in a variety of malignancies by acting through the PI3K/AKT/mTOR signaling pathway." (PMID 38136377, 2023). "Due to the fact that the mechanism of action of Pentraxin 3 can be described as pro- and anti-cancer, its specific role in the course of individual cancers is difficult to determine." (PMID 38136377, 2023). "PTX3 is expressed and released by different cell types at the site of inflammation, e.g., innate immune cells, stromal cells, as well as cancer cells, in contrast with CRP or SAP, which are primarily produced within the liver due to IL-6 mediated inflammation." (PMID 38136377, 2023). "Our findings brought to light that PTX3 had a close and positive association with most ICIs (CD274, CTLA4, HAVCR2, LAG3, PDCD1, PDCD1LG2, TIGIT, and SIGLEC15) in TCGA cancers, except TGCT." (PMID 36139597, 2022). "Through systematic and comprehensive bioinformatics analysis and in vitro experiments, we revealed the immune infiltrating patterns of PTX3 in cancer based on large‐scale samples." (PMID 35855654, 2022). "Together with ADAM12, the glycoprotein pentraxin-3 (PTX3) is also a critical protein promoting cell invasiveness of various cancers." (PMID 36009036, 2022). "Some BIIGs were upregulated in multiple cancer types: Top2a, Mki67, Rrm2, Mcm6, and Spp1 were upregulated in more than eight cancer types, while Emp1, Ptx3, and Socs3 were upregulated in seven cancer types." (PMID 36605216, 2022). "In this comprehensive study, the clinical and prognostic values of PTX3 in pan-cancers were identified via bioinformatics analyses." (PMID 36139597, 2022). "Monoclonal antibodies that recognise the C‐terminus of PTX3 and disrupt the interaction between PTX3 and CD44 were developed to validate the PTX3/CD44 axis‐induced protumour effects on cancer development, metastasis/invasion and stemness." (PMID 35090088, 2022). "First, we focused on two hotspots, the COVID-19 biomarker PTX3 and immunotherapy, synthetically underscoring their importance in human cancers." (PMID 36139597, 2022). "After knockout of PTX3 in a variety of animal cancer models, expression levels of M2 macrophage related genes are upregulated." (PMID 35739102, 2022).
cancer (continued). "It should also be noted that PTX3 positively correlated with CD80, an essential costimulatory molecule in activating T cells, which further proved the dual roles of PTX3 in cancer immunity." (PMID 35855654, 2022). "Some BIIGs were downregulated in various cancers, especially Il1r1, Srgn, Emp1, Ptx3, Socs3, and Cebpd, which were downregulated in at least seven cancer types." (PMID 36605216, 2022). "In other words, PTX-3 correlates significantly with patient prognosis, similar to other types of cancer (such as prostate, breast, and ovarian)." (PMID 36499628, 2022). "We conducted a bioinformatics analysis and fundamental experiments to investigate the specific and paramount roles of PTX3 in cancers." (PMID 36139597, 2022). "Overall, we conclude that PTX3 is expressed in PDAC tissues, and is produced by stromal and cancer cells, likely in response to an associated inflammation that characterizes KRAS-harboring tumors, or in response to local tissue damage." (PMID 35681634, 2022). "Utilizing functional KEGG and Hallmark terms through GSEA, we explored the biological mechanisms of PTX3 in pan-cancers." (PMID 36139597, 2022). "Epigenetic regulation makes an important impact on the regulation of PTX3 transcription in cancer cells." (PMID 35090088, 2022). "Although pentraxin 3 was initially described as an oncosuppressor, its expression in cancers has been shown to differ depending on the cancer types." (PMID 36139106, 2022). "PTX-3 is emerging as a promising non-invasive tool for cancer diagnosis, evaluating prognosis, monitoring chemotherapy, and novel management strategies." (PMID 36499628, 2022). "While future investigations are needed, PTX-3 is emerging as a promising tool for cancer’s diagnosis and prognosis, and also treatment monitoring." (PMID 36499628, 2022). "Further, in most cancers, PTX3 was involved in multiple immune regulation‐related biological pathways, such as the activation and proliferation of fibroblasts, and the immune defense and cytotoxicity of T cells and macrophages." (PMID 35855654, 2022). "Similar to the effect of RI37 and P2rdAD9, in vitro assays showed that Ab‐10 and Ab‐49 also inhibited PTX3‐induced signalling pathways, the transcription of known downstream genes, and the cancer features of migration/invasion and stemness." (PMID 35090088, 2022). "Taken together, PTX3 was assumed to play dual roles in enhancing and suppressing cell‐mediated cancer immunity." (PMID 35855654, 2022). "With the genetic alteration analysis of PTX3, we observed that PTX3 yielded a significant alteration to a great extent in diverse cancers." (PMID 36139597, 2022). "Our study derives mainly from the computational analysis of genomic data and in vivo and in vitro tests are needed to determine the exact mechanisms of PTX3 in cancers." (PMID 36139597, 2022). "An in vivo study demonstrated that loss of pentraxin 3 (PTX3) in stromal cells significantly decreased the metastasis and growth of cancer cells." (PMID 35090088, 2022). "As an activator of the complement pathway of the innate immune system, PTX3 is a key homeostatic component in the immune response, tissue remodeling, and cancers." (PMID 36139597, 2022). "In particular, this information shows that the potential role of PTX3 in modulating the innate immune response in cancer is supported by experimental evidence." (PMID 34048179, 2021). "We also described the ambivalent role of cellular senescence and identified in PTX3 a possible common mediator between systemic inflammation, cancer, and premature aging." (PMID 34572075, 2021). "Intriguingly, we found that silencing PTX3 significantly suppressed the invasion capacity of stellate and cancer cells, in both co-cultures and monoculture experiments." (PMID 34188166, 2021). "Though epithelial source for PTX3 secretion in other cancer tissues is described, our data demonstrate that in PDAC the dominant secretion is from PSC." (PMID 34188166, 2021).
cancer (continued). "Based on its quaternary structure, PTX3 interacts with a series of ligands, playing multiple roles in different settings, such as cardiovascular diseases, fertility and cancer." (PMID 34856980, 2021). "Conversely, cancer cells showed minimal PTX3 and HA expression and strong TSG-6 staining in the cytoplasm." (PMID 34188166, 2021). "PTX3 is secreted by dendritic cells, macrophages, and fibroblasts and is actively involved in the regulation of inflammation, tissue remodeling, and cancer." (PMID 34745101, 2021). "PTX3 in the pentraxin family is an immunomodulatory factor involved in angiogenesis, proliferation, and immune escape in cancer." (PMID 34745947, 2021). "Several studies identified an enrichment of PTX3 in EVs correlated with pro-inflammatory conditions during the progression of different cancer types." (PMID 33931080, 2021). "Among the entire pentraxins family members, PTX3 is implied to achieve reduced expression in several malignant cancers' progressions." (PMID 33746606, 2021). "The IHC scores of PTX-3 in malignant tumors were significantly higher than those in normal ovarian epithelial and borderline tissues." (PMID 33952272, 2021). "PTX3 mRNA manifestation levels were significantly increased in both cancer cells compared to the control group (NC).Furthermore, PTX3 protein levels were also raised suggestively." (PMID 32194791, 2020). "Pentraxin-3 (PTX3) belongs to the pentraxine family, innate immune regulators involved in angiogenesis, proliferation and immune escape in cancer." (PMID 32345771, 2020). "Recent researches have indicated that PTX3 is involved in immune response, inflammation, as well as cancer, and is greatly controlled by numerous cytokines." (PMID 32194791, 2020). "In a chemically induced carcinogenesis model of PTX3‐deficient mice, defective recruitment of CFH to cancer cells results in higher levels of the anaphylatoxins C3a and C5a due to complement activation." (PMID 33708358, 2020). "Here, we investigated the impact of the natural FGF trap long-pentraxin 3 (PTX3) on the determination of primary cilium extension in zebrafish embryo and cancer cells." (PMID 32630309, 2020). "PTX3 expression profiles of pan-cancer and normal tissue were obtained from the TCGA database and the Getx database." (PMID 32984316, 2020). "In summary, our study demonstrates the ability of the natural FGF trap PTX3 to exert a modulatory effect on primary cilium in embryonic development and cancer." (PMID 32630309, 2020). "Nevertheless, the downstream molecular event of PTX3, especially the possible receptor of PTX3 to transmit the signal of the secretory protein into cells, is yet to be discovered before PTX3 targeting becomes practical for cancer treatment." (PMID 32427938, 2020). "Together, these findings demonstrate the ability of the natural FGF trap PTX3 to exert a modulatory effect on primary cilium in embryonic development and cancer." (PMID 32630309, 2020). "We also demonstrate that SH3RF3 contributes to the assembly of MKK-JIP-JNK complex, leading to activation of JNK and upregulation of PTX3 expression for CSC regulation in cancer cells." (PMID 32427938, 2020). "In the present research, we investigated the effect of the modulation of PTX3 expression on primary cilium extension in zebrafish embryo and cancer cells." (PMID 32630309, 2020). "PTX3 is expressed by many types of cancers, and it can bind to circulating factor H, tethering this inhibitor to cells and suppressing complement activation within the TME." (PMID 33167384, 2020). "Studies reported here finally show that PTX3 is involved in tuning carcinogenesis through the modulation of cancer-related inflammation or angiogenesis in specific cancer types." (PMID 31019517, 2019). "Beside an evaluation of PTX3 as soluble biomarker in cancer, some reports also investigated PTX3 expression in cancer tissues." (PMID 31019517, 2019).